CCL21 (C-C motif chemokine ligand 21)
Diseases named in the same sentence as CCL21 in open-access papers (continued):
Sharing a sentence is not in itself a finding about the gene and the disease.
glioma (8 papers, 2012 to 2024). A benign or malignant brain and spinal cord tumor that arises from glial cells (astrocytes, oligodendrocytes, ependymal cells). "The data showed that anti-CCL21 antibodies reduced the survival time after RT of mice bearing gliomas overexpressing VEGF-C." (PMID 35301438, 2022). "Also, CCL21 is secreted by glioma cells and tumor stromal cells and has been shown to directly promote glioma cell growth in vitro." (PMID 22312408, 2012). "CCL21 and CCR7 expression in human GBM tumors, therefore, correlates with glioma malignancy and patient survival." (PMID 37314567, 2023). "By QPCR, we observed elevated expression levels of both CCR7 and CCL21 in a cohort of 14 WHO grade IV GBM compared to 11 LGG patients (WHO grade I, II, and III gliomas)." (PMID 37314567, 2023). "In previous studies, the molecular mechanisms of HTR1A, CCL13, CCL21, and CCL27 in gliomas remained unclear." (PMID 33503296, 2021). "CXCL10, CCL13, SAA1, and CCL27 were more highly expressed in elderly, high‐grade, 1p19q non‐codel, IDH‐wildtype glioma patients, while SSTR5, CCL21, and HTR1A expressions were low in these malignant clinicopathological features of gliomas." (PMID 33503296, 2021). "By immunostaining, CCL21 expression was also higher in neoplastic samples than in normal tissues, and increased with glioma grades, with highest expression in WHO grade IV GBMs." (PMID 37314567, 2023). "Indeed, the mice with glioma that were treated with lymphatic protein blockers, such as chemokine (C-C motif) ligand 21 (CCL21) and C chemokine receptor type 7 (CCR7), did not demonstrate improvements after receiving this anti-tumor therapy." (PMID 36559105, 2022). "Likewise, when engineered vaults packaged with CCL21-INT (CCL21 being a chemokine able to attract a variety of immune cells) were delivered intratumorally into murine tumor models—i.e., either Lewis Lung tumor or glioma; this resulted in a substantial growth inhibition." (PMID 33572350, 2021).
lung adenocarcinoma (8 papers, 2018 to 2025). A carcinoma that arises from the lung and is characterized by the presence of malignant glandular epithelial cells. "One study compared GM.CD40L versus GM.CD40L plus CCL21 in lung adenocarcinoma patients who received with ≥ 1 line of treatment (NCT01433172)." (PMID 39179939, 2025). "For instance, tobacco exposure, which triggers inflammatory reactions, has been connected to increased TLS abundance and CCL21 in lung adenocarcinoma patients, correlating with the response to immunotherapy." (PMID 38111571, 2023). "In the current study, the data demonstrate that PD-1 blockade augments T cell and DC activity of CCL21-DC tumor Ag vaccine in the TME to eradicate K-RasG12Dp53null lung adenocarcinoma." (PMID 32570793, 2020). "We evaluated PD-1 blockade combined with CCL21-DC tumor Ag pulsed vaccine in the K-RasG12Dp53null murine model of lung adenocarcinoma." (PMID 32570793, 2020). "Here, we compared GM.CD40L versus GM.CD40L plus CCL21 (GM.CD40L.CCL21) in lung adenocarcinoma patients with ≥ 1 line of treatment." (PMID 30209589, 2018). "Lymphatic ECs promote lymph node metastasis of lung adenocarcinoma via the CCL21 signaling axis." (PMID 39003681, 2024). "On the bases of improved outcomes in the animal model shown with GM.CD40L plus CCL21 and the limited options for previously treated patients with advanced or stage IV lung adenocarcinoma, we conducted a single-center phase I/randomized phase II trial to evaluate GM.CD40L vaccine plus/minus CCL21." (PMID 30209589, 2018). "The co-culture system of primary lymphatic endothelial cells and lung adenocarcinoma cells found that TNF-α significantly increased the concentration of CCL21 in lymphatic endothelial cell culture medium and could promote the invasion and metastasis of lung adenocarcinoma cells." (PMID 33158173, 2020). "On the other hand, in lung adenocarcinoma cells, chronic hypoxia does not change the expression of CCL19/ELC and CCL21/SLC." (PMID 32781743, 2020).
prostate carcinoma (8 papers, 2019 to 2024). A carcinoma that arises from epithelial cells of the prostate gland. "CCL21 seems to be implicated in the microenvironment of primary prostate cancer as well." (PMID 39146303, 2024). "CCL5 belongs to the family of C-C chemokines as do CCL7, CCL8, and CCL21, which were also upregulated in prostate cancer lung metastases." (PMID 39146303, 2024). "CCL21 has been shown to promote prostate cancer cell migration." (PMID 39146303, 2024). "In addition, CCL19 and CCL21 migrated dendritic cells in prostate cancer to inhibit cancer progression." (PMID 38075694, 2023). "Furthermore, TNF-α leads to the induction of CCR7 expression and the CCL21/CCR7 axis may increase the metastatic potential of prostate cancer cells in lymph node metastasis." (PMID 35517503, 2022). "CCL21, a ligand of CCR7 that is secreted by fibroblastic reticular cells in lymph nodes and is abundant in the T-cell zone of the lymph node, was found to promote prostate cancer cell migration via protein kinase p38 phosphorylation." (PMID 30871130, 2019).
hepatocellular carcinoma (7 papers, 2013 to 2024). A malignant tumor that arises from hepatocytes. "When CCL21-transfected DCs were injected intratumorally in mice bearing hepatocellular carcinoma (HCC), mice exhibited delayed tumor progression, increased intratumoral T cell infiltration and overall improved survival." (PMID 24967094, 2013). "CCL21+ endothelial cells (c3) were significantly reduced in hepatocellular carcinoma." (PMID 33532508, 2021).
liver cancer (7 papers, 2013 to 2025). An epithelial or non-epithelial malignant neoplasm that arises from the liver. "The CCR7/CCL21 transport system involved in intrahepatic lymphocyte transport, as elucidated in our study, may be strongly associated with lymphatic and intrahepatic metastasis of malignant liver tumors." (PMID 40038879, 2025). "Through employing a public data set (GSE125449) containing single-cell RNA sequencing data of 19 patients with liver cancer for bioinformatics analyses, we found that CCL21 in liver cancer was mainly derived from stromal cells like fibroblasts and epithelial cells." (PMID 38367070, 2024).
lymphoma (7 papers, 2014 to 2024). A malignant (clonal) proliferation of B- lymphocytes or T- lymphocytes which involves the lymph nodes, bone marrow and/or extranodal sites. "Together, lymphoma-associated remodeling of the FRC network abrogated the CCL21 guidance track for immune cell trafficking within the LN parenchyma." (PMID 34706240, 2021). "Of note, CCR4, the receptor of TARC/CCL17 and CCL21, was also among the genes significantly downregulated in HLA‐I+ lymphomas." (PMID 38836098, 2024). "Conditional knockout of the LTβR in ECs (Cdh5CreERT2xLtbrfl/fl referred to as Ltbrfl/fl) caused a reduction of PNAd, CCL21, and ICAM1 expression in BECs, similar to the dedifferentiation observed in HECs during lymphoma challenge." (PMID 34706240, 2021). "An effort to restore CCL21 expression in FRCs, as mediated by LTβR antibody stimulation or overexpression of LTβR ligands in lymphoma cells, was unsuccessful, indicating that FRCs require mechanosensitive signaling to gain a mature myofibroblastic state." (PMID 34706240, 2021). "In sum, our data suggest that HEV dedifferentiation is caused by a lymphoma-induced cascade that begins with an abrogation of lymph flow in conduits and a downregulation of FRC-derived CCL21 expression." (PMID 34706240, 2021). "Conceivably, the reduced abundance of CCL19/CCL21 in LN of FL is lymphoma instructed and contributes to evasion from anti-tumor immunity." (PMID 34778050, 2021). "This could likely be a result of deregulated CCL21 expression in FRCs or a secondary effect due to the physical disruption of the lymph architecture in rapidly expanding LNs during lymphoma progression." (PMID 34706240, 2021). "In the lymphoma-induced LN remodeling cascade, HEV dedifferentiation and loss of functionality emerged as a consequence of disturbed conduit channeled lymph flow, aberrant extracellular matrix (ECM) deposition, and the subsequent deregulation of CCL21 intranodal DC migration routes." (PMID 34706240, 2021). "Our immunohistochemical analysis of the CCL19 and CCL21-ligands of CCR7 demonstrated that the lymphoma cells expressed CCL19, but that CCL21 expression was low in the malignant cells." (PMID 35887224, 2022). "Moderate CCL19 expression was detectable on the vast majority of the lymphoma cells in both of the DLBCL subtypes, whereas CCL21 protein expression was found in less than half of the analyzed samples (18 of 43)." (PMID 35887224, 2022). "Inhibition of LTβR signaling by anti- LTβR antibody or knockdown of LTα impaired cell interaction between lymphoma cell and stromal cell, potentially by disrupting production of CCL19 and CCL21 by stromal cells which are ligands for CCR7." (PMID 25211095, 2014). "Combining the CCR7 expression with the CCL19 and CCL21 expression pattern, it seems that CCR7 signaling is altered in the lymphoma setting compared to the non-neoplastic condition." (PMID 35887224, 2022). "In contrast to infection models, lymphoma did not allow a recovery of HEVs, FRC-derived CCL21 expression, or the conduit network, although lymphoma B cells potentially can activate LTβR signaling." (PMID 34706240, 2021).
Autoimmunity (6 papers, 2011 to 2025). The occurrence of an immune reaction against the organism's own cells or tissues. "Though these data are only associative, given that Ccl21 is expressed almost exclusively by LECs in the human lung, these results suggest that lymphatic markers may correlate with an autoimmune emphysema phenotype, even among patients with the same stage of COPD." (PMID 39437762, 2025). "While naive T cells depend on CCL21 for their recruitment to secondary lymphoid organs, the trafficking of memory T cells was found to be dependent on CCL21 in autoimmunity." (PMID 37426658, 2023). "Notably, besides migration, CCL19/CCl21 chemokines have been correlated with autoimmunity and immune suppression indicating an important additional role balacing immunity and tolerance." (PMID 21483789, 2011).
bladder cancer (6 papers, 2015 to 2024). "CCL21/CCR7 enhanced bladder cancer cell proliferation and facilitated migration and invasion by increasing levels of MMP-2 and MMP-9." (PMID 33146700, 2020). "Clinicopathological data also show that chemokines and their receptors are involved in tumor lymphatic metastasis; for example, CCL21/CCR7 expression is related to poor outcomes in urinary bladder cancer." (PMID 29599774, 2018). "CCL21 may strongly increase T24 cell migration and invasion at high concentrations and thus facilitate bladder cancer metastasis." (PMID 25798926, 2015). "Therefore, the secretion level of CCL5 and CCL21 was measured to verify whether bladder cancer cells could induce the recruitment of DCs after radiotherapy in this study." (PMID 39231199, 2024). "Our results indicate that CCL21/CCR7 may promote bladder cancer development and metastasis." (PMID 25798926, 2015). "CCL21/CCR7 may promote bladder cancer development and metastasis." (PMID 25798926, 2015). "However, the possible role of CCL21/CCR7 in bladder cancer development and progression remains unclear." (PMID 25798926, 2015). "Combining the results of bladder cancer cell apoptosis, HMGB1 protein expression, and chemokine CCL21 secretion in this paper, it can be hypothesized that BT-B cells received the highest radiation dose of 10 Gy have the maximal effect on imDC." (PMID 39231199, 2024).
colon carcinoma (6 papers, 2016 to 2024). "According to one study, CCL21/CCR7 played an important role in human colon cancer metastasis." (PMID 36829431, 2023). "Finally, CCL21 has been shown to play a role in colon cancer metastasis." (PMID 37446056, 2023). "Furthermore, we found that colon cancer tissues exhibited higher expressions of CCL20 and CXCL16, but similar expressions of CCL21 and CXCL10 as compared with unaffected tissue, which is in line with previous studies." (PMID 27517754, 2016).
viral infection (6 papers, 2014 to 2025). "These aged FRCs formed disrupted reticular cell networks and produced less T cell chemokines CCL19 and CCL21 following viral infection." (PMID 36802099, 2023). "Suppression of the CCR7 and CCL19/CCL21 axis results in dysfunction of T-cells during viral infection." (PMID 32731586, 2020). "CXCL13, CCL19 and CCL21 have previously been shown to be essential components of the local airway immune response to viral infection and to be involved in iBALT formation, a recognised feature of long term pathogen exposure." (PMID 24847941, 2014).
breast tumor (5 papers, 2017 to 2023). "In fact, we have previously demonstrated that DMBA exposure before cancer initiation leads to the development of immunogenetic spontaneous breast tumors, at least in part, due to the induction of CCL21 expression in tumor cells." (PMID 37843274, 2023). "This study showed that ILC3s recruitment into a breast tumor model is dependent on chemokine (C-C motif) ligand 21(CCL21)." (PMID 36341381, 2022). "The overall impact of CCL21 on breast tumor progression can display opposite effects depending on the cell population in which CCL21 and CCR7 receptor are expressed." (PMID 34160019, 2021). "The role of the CCL21/CCR7 axis in the breast tumor microenvironment was further analysed for the tumor cell interaction with stromal cells, namely the cancer associated fibroblasts." (PMID 28416768, 2017). "Therefore, Ifng activates the Ccl19/Ccl21/Ccr7 axis between breast tumors and SRC-3 KO Tregs to signal the recruitment of SRC-3 KO Tregs into breast tumors." (PMID 37253006, 2023).
cervical carcinoma (5 papers, 2017 to 2024). A carcinoma arising from either the exocervical squamous epithelium or the endocervical glandular epithelium. "For instance, the expression of CCR7 in cervical cancer tumor cells can direct them toward lymph nodes that express CCL21, one of its chemokine ligands." (PMID 39200672, 2024). "Chronic hypoxia causes an increase in mRNA expression of CCL19/ELC and CCL21/SLC in cervical cancer cells." (PMID 32781743, 2020). "Among these, SPP1 and CCl21 were found to be potent secretary molecules contributing to the progression of cervical cancer; thus, the current study projects these genes as potential therapeutic targets in general for cervical cancer and in specific for the Indian population." (PMID 33829064, 2021). "Downregulation of CCL21 is attributed to upregulated expression of SPP1 in cervical cancer tissue." (PMID 33829064, 2021). "A large number of studies have demonstrated that chemokines are involved in the progression, migration, and survival of cancers, such as CXCL12 (ENSG00000107562), CCL21 (ENSG00000137077), and especially CCL19 (ENSG00000172724), which is associated with progression of cervical cancer." (PMID 28970820, 2017). "The candidate genes SPP1, FOXM1, LYN, COL6A3, CCL21, TTK and MELK at mRNA level, emerge as promising candidate markers for cervical cancer prognosis and also emerge as potential therapeutic drug targets." (PMID 33829064, 2021). "CCL21 was found to be significantly downregulated as compared to COL6A3 as shown in, and all these genes behaved similarly as seen in the microarray data and our study is in accordance with other published reports of cervical cancer." (PMID 33829064, 2021).
Cognitive impairment (5 papers, 2020 to 2025). Abnormal cognition is characterized by deficits in thinking, reasoning, or remembering. "Serum CCL21 is an independent risk factor for cognitive impairment after SCI." (PMID 33376730, 2020). "The hsa-miR-933/RELB/CCL21 regulatory axis was considered a potential culprit in the development of both HF and cognitive disorders." (PMID 37288268, 2023). "Based on PPI networks, the hsa-miR-933/RELB/CCL21 regulatory axis was considered a potential culprit in the development of both HF and cognitive disorders." (PMID 34595235, 2021). "This work will generate fresh insight into the theoretical basis for clinical translation by demonstrating that the hsa-miR-933/RELB/CCL21 regulatory axis played an important role in HF and cognitive disorders." (PMID 34595235, 2021). "We will also explore the mechanisms of the hsa-miR-933/RELB/CCL21 regulatory axis in the development of HF and cognitive disorders by performing animal and cellular experiments." (PMID 34595235, 2021). "The findings suggested a potential hsa-miR-933/RELB/CCL21 regulatory axis correlated with HF and neurological disorders (or cognitive impairment), according to PPI networks." (PMID 34595235, 2021). "After adjusting for confounding factors such as age, gender, BMI, TG, LDL-C, FBG, SBP, and DBP, serum CCL21 still has a predictive effect on cognitive impairment after SCI." (PMID 33376730, 2020). "Further research found that serum CCL21 can be used as a potential biomarker for the diagnosis of cognitive impairment after SCI." (PMID 33376730, 2020). "Multivariable analyses showed that serum CCL21 level is an independent prognostic factor of cognitive impairment in SCI." (PMID 33376730, 2020). "Multivariable analyses showed that serum CCL21 is an independent predictor of cognitive impairment after SCI (β = 0328, p = 0.027)." (PMID 33376730, 2020). "Similarly to CCL21, CCL23 was associated with progression from mild cognitive impairment (MCI) to Alzheimer’s disease (AD)." (PMID 40149697, 2025). "The hsa-miR-933/RELB/CCL21 regulatory axis was speculated to function critically in HF and cognitive disorders." (PMID 34595235, 2021). "CCL21 has been reported in animal studies on cognitive impairment after SCI." (PMID 33376730, 2020). "The purpose of this study is to explore whether serum CCL21 can be used as a potential biomarker of cognitive impairment in SCI." (PMID 33376730, 2020). "Recent preclinical work 80 has begun to elucidate the underlying mechanisms of cognitive impairments following SCI, such as neuroinflammation in the brain, distal release of a potent microglial activators (i.e., CCL21) through anterograde and retrograde pathways, or systemic immune dysfunction." (PMID 33052221, 2020). "The accumulation of CCL21 in the brain may be a potential target of cognitive impairment after SCI." (PMID 33376730, 2020).